CARM1 (coactivator associated arginine methyltransferase 1)
Diseases named in the same sentence as CARM1 in open-access papers (continued):
Sharing a sentence is not in itself a finding about the gene and the disease.
cancer (continued). "It has been discovered that CARM1, an oncogenic protein, is overexpressed in a number of cancers, including breast, ovarian, hematopoietic, liver, pancreatic, colorectal, prostate, bone, oral, lung, and melanoma." (PMID 38619752, 2024). "CARM1 participates in the ongoing inflammatory response, which is crucial to the malignant transformation, cancer propagation and metastasis." (PMID 38619752, 2024). "This comprehensive understanding of CARM1’s multifaceted functions positions it as a promising target for therapeutic interventions in the complex landscape of cancer biology." (PMID 38619752, 2024). "Previous studies have suggested that CARM1 has been identified as an oncogene, which regulates the malignant behaviors of cancer cells through various signaling pathways." (PMID 39266534, 2024). "Several recent reviews have explored CARM1’s potential as a therapeutic target in cancers, shedding light on its role in the pathogenesis of various malignancies." (PMID 38619752, 2024). "Oncogenic signals in various cancers intricately modulate the PTMs of CARM1, thereby changing its enzymatic activity and substrate interaction affinities." (PMID 38619752, 2024). "CARM1 skillfully directs its coactivator activity in cancers by methylating histone H3 at R2, R17, and R26." (PMID 38619752, 2024). "In conclusion, CARM1 is a potential cancer biomarker and CARM1, HIF1A, and CDK4 are positively correlated in multiple cancers." (PMID 38476024, 2024). "CARM1 is a crucial regulator of metabolic reprogramming in cancers, including glucose, glutamine, lipid, glycogen and one-carbon metabolism." (PMID 38619752, 2024). "Coactivator-associated arginine methyltransferase 1 (CARM1), pivotal for catalyzing arginine methylation of histone and non-histone proteins, plays a crucial role in developing various cancers." (PMID 38619752, 2024). "Tissue microarray analysis revealed the significant upregulation of CARM1 expression in carcinomas from multiple tissues compared with adjacent normal tissues." (PMID 38476024, 2024). "In the future, the treatment of an SCLC GEMM with CARM1 inhibitors will further determine their therapeutic values of targeting this pathway for this cancer type." (PMID 36690626, 2023). "CARM1 inhibition is expected to have a positive impact on the lives of patients afflicted with a large number of cancer types." (PMID 37536629, 2023). "Here, we will focus on why CARM1 should be regarded as a viable therapeutic target in several different cancer types." (PMID 37536629, 2023). "CARM1 is overexpressed in many different cancer types, and often promotes transcription factor programs that are co-opted as drivers of the transformed cell state, a process known as transcription factor addiction." (PMID 37536629, 2023). "The existence of these isoforms with different cancer-related functions complicates analyses that consider only total CARM1 protein levels." (PMID 37536629, 2023). "In the context of cell fate decisions, Carm1 (Prmt4) is of particular interest as it is crucial for early embryo development, muscle regeneration, adipogenesis, and cancer." (PMID 37365888, 2023). "Consistent with CARM1 being considered a contributor to cancer progression, immunohistochemistry (IHC) staining and Western blotting results also showed that CARM1 was upregulated in CRC tissues." (PMID 37946697, 2023). "It has been reported in the literature that CARM1 is overexpressed in a variety of cancer types (e.g., breast, ovarian, pancreatic, liver, and hematologic tumors)." (PMID 37477799, 2023). "The transcriptional coactivator CARM1 has been reported to be widely involved in biological processes such as cell differentiation, autophagy, metabolism and cancer." (PMID 35525959, 2022). "Emerging evidence suggests that CARM1 functions as an oncogene in human cancers, and it is often highly expressed in several cancer types, such as breast, colon, and prostate cancers." (PMID 36307405, 2022).
cancer (continued). "In most TCGA tumors, the expression of CARM1 is positively correlated with the infiltration of cancer-related fibroblasts, especially in ACC, KIRC, MESO, THYM and UVM." (PMID 35033016, 2022). "Since autophagy is recognized as a double-edged process in the progression of cancer, we explored the effect of CARM1 and the autophagy induction on GC cell proliferation." (PMID 35246137, 2022). "Our work, for the first time, used multiple databases containing The Cancer Genome Atlas (TCGA) project, cBioPortal, Human Protein Altas (HPA) and so on to conduct a comprehensive pan-cancer analysis of CARM1." (PMID 35033016, 2022). "Next, the TIMER2 approach was applied to compare the expression difference of CARM1 between various cancer types and corresponding normal tissues." (PMID 35033016, 2022). "For example, BAF155 methylation drives cancer metastasis, providing the foundation for employing CARM1 inhibitors in cancer therapy." (PMID 34865122, 2021). "High expression of CARM1 was linked to a poor prognosis in a variety of cancer types, including KIRP, LUAD, ACC, BLCA, LGG, and SKCM, demonstrating CARM1 as a possible and effective prognostic marker for pancancer." (PMID 34745258, 2021). "Early Studies have shown that CARM1 is often highly expressed in human cancers, including breast, ovarian, prostate, colorectal cancer and so on." (PMID 33593309, 2021). "Given their low cytotoxicity and strong anti-metastasis effects, pharmacological inhibitors of CARM1 should be further exploited as anti-cancer drugs for the treatment of broad types of solid tumors in which CARM1 is overexpressed." (PMID 34865122, 2021). "We used the TCGA, TIMER, and GTEx databases to determine the level of CARM1 expression in cancers and normal tissues in the first stage of our study." (PMID 34745258, 2021). "The targeting CARM1-interacting proteins and genes linked to CARM1 expression were evaluated for many pathway enrichment studies to determine the CARM1 gene's molecular mechanism in cancer genesis and progression." (PMID 34745258, 2021). "High levels of CARM1 expression have been observed in several major cancer types, including breast, colon, and prostate." (PMID 34493732, 2021). "Our data show that pharmacological inhibition of the IRE1α/XBP1s pathway alone or in combination with immune checkpoint blockade represents a therapeutic strategy for CARM1-expressing cancers." (PMID 34493732, 2021). "We, therefore, investigated the possible association between the infiltration level of various immune cells and the expression of the CARM1 gene in TCGA cancer types using the CIBERSORT, TIMER, QUANTISEQ, CIBERSORT-ABS, MCPCOUNTER, EPIC, and XCELL algorithms." (PMID 34745258, 2021). "In this study, the TCGA project and GEO databases were used for the first time to perform a pancancer review of CARM1 for evaluating the possible molecular mechanism of CARM1 in relation to cancer progression and clinical prognosis." (PMID 34745258, 2021). "Clinical data and TCGA RNA-seq (downloaded from UCSC Xena) were used to examine the prognosis of 33 TCGA cancer types to see if CARM1 has an effect on cancer patient prognosis." (PMID 34745258, 2021). "The current study focused on CARM1 expression in the cytoplasmic portion of cancer cells and assessing the complex TME via tissue microarray." (PMID 34745258, 2021). "According to recent research, CARM1 enhances cancer progression and metastasis by catalyzing the methylation of tumor proteins which leads to an investigation of the molecular mechanism, revealing CARM1's correlation with cancer genesis and progression." (PMID 34745258, 2021). "Our findings indicate that inhibition of the IRE1α/XBP1s pathway alone or in combination with immune checkpoint blockade represents a therapeutic strategy for a number of cancer types with frequent CARM1 overexpression including HGSOCs6–8." (PMID 34493732, 2021).
cancer (continued). "Then, to evaluate CARM1's probable mechanisms of action, we looked at its expression in distinct molecular subtypes of malignant tumors." (PMID 34745258, 2021). "Multiple lines of evidence suggest that CARM1 plays crucial roles in modulating a variety of cellular processes, such as transcription activation, RNA processing, tumorigenesis and cancer progression, cell growth/differentiation and apoptosis." (PMID 32487779, 2020). "Emerging evidence also supports the pathological roles of CARM1 in human disease, particularly in cancer." (PMID 32206101, 2020). "Increased CARM1 expression and/or activity has been reported in a variety of cancer types, including breast, prostate, colorectal, lung and liver cancer, and its higher expression often correlates with poor prognosis 22-30." (PMID 32206101, 2020). "The future challenge would be to determine the impact of CARM1 in autophagy in relation to aging and age-related diseases such as cancer and neurodegenerative diseases." (PMID 33293536, 2020). "CARM1 is a cancer-relevant protein arginine methyltransferase that regulates many aspects of transcription." (PMID 31657716, 2019). "We also analyzed RNA-seq data available in TCGA (The Cancer Genome Atlas) to determine any possible correlations in RNA expression of CARM1 and YY1 in different cancer types." (PMID 31217904, 2019). "We therefore discovered a CARM1-addiction mechanism of cancer metastasis and developed a chemical probe to target this process." (PMID 31657716, 2019). "Blocking CARM1 switched off genes involved in cell movement and stopped cancer cells from travelling through 3D gels." (PMID 31657716, 2019). "Although this cancer relevance inspired the development of CARM1 inhibitors, many small-molecule CARM1 inhibitors lack target selectivity or cellular activity, two essential criteria of chemical probes." (PMID 31657716, 2019). "This work is a step towards making a drug that can block CARM1 in cancer cells, but there is still further work to be done." (PMID 31657716, 2019). "It has been reported that miR-195 suppresses the proliferation, migration, invasion and radiosensitivity of cancer cells through directly targeting some oncogenes, including CARM1, YAP, GDPD5 and WNT3A." (PMID 30487160, 2018). "Together, these results indicate that pharmacological inhibition of EZH2 represents a novel therapeutic strategy for CARM1-expressing cancers." (PMID 29434212, 2018). "High levels of CARM1 expression have been observed in several cancer types, including breast, colon, and prostate." (PMID 29434212, 2018). "In vitro experiments using genetic knockdown of CARM1 have shown anti-proliferative effect of knockdown in several cancer cell lines." (PMID 29269946, 2017). "Specifically, we discovered in vivo over 300 CARM1-dependent arginine methylation events, corresponding to >130 novel CARM1 protein substrates, many of which have documented cancer-relevant functions." (PMID 28537268, 2017). "The majority of these studies were conducted in epithelial-derived cancer cell lines, based on reports of CARM1 overexpression in these indications." (PMID 29269946, 2017). "EZM2302 is a validated chemical probe suitable for further understanding the biological role CARM1 plays in cancer and other diseases." (PMID 29269946, 2017). "Though CARM1 overexpression has been reported in multiple cancer types, its role in oncogenesis is not fully understood." (PMID 29269946, 2017). "PRMT4 or coactivator-associated arginine methyltransferase 1 (CARM1) is a propitious target for cancer therapy; however, few CARM1 substrates are known, and its mechanism of substrate recognition is poorly understood." (PMID 28537268, 2017). "CARM1 overexpression has been reported in multiple cancer types and has been shown to modulate oncogenic pathways in in vitro studies." (PMID 29269946, 2017). "Many of these substrates have cancer-relevant functions and thus are possible mediators of CARM1's oncogenic potential." (PMID 28537268, 2017).
cancer (continued). "Overexpression of CARM1 has been observed in multiple cancer types including myelocytic leukemia and breast, prostate, lung, and colorectal carcinomas, making it a potential target for anticancer therapy." (PMID 27872854, 2016). "Overexpression of coactivator associated arginine methyltransferase 1 (CARM1), a protein arginine N-methyltransferase (PRMT) family enzyme, is associated with various diseases including cancers." (PMID 27872854, 2016). "Coactivator-associated arginine methyltransferase 1 (CARM1) is a coactivator for ERα and cancer-relevant transcription factors, and can methylate diverse cellular targets including histones." (PMID 26030442, 2015). "We analyzed CARM1 levels using tissue microarrays with over 800 histological samples from 549 female cancer patients from the US and Nigeria, Africa." (PMID 23663560, 2013). "Consistent with this concept, our result also shows only a small part of luminal A subtype cancer tissue overexpress nuclear CARM1." (PMID 23915145, 2013). "Citrullination of histones has been described in relation to its capacity to antagonize arginine methylation by CARM1, but its role in cancer diseases is starting to be delineated now." (PMID 23016851, 2013). "Tissue microarray was used to determine the pattern of expression of CARM1 in human cancers by immunohistochemistry." (PMID 20462455, 2010). "Additionally, numerous new PRMT4 substrates continue to be identified, but clinically applicable cancer treatment strategies based on CARM1 remain to be explored." (PMID 41154773, 2025). "Given the convergence of CARM1's role in both cancer and metabolic disorders, and metformin's diverse therapeutic effects, we sought to investigate whether CARM1 serves as a potential therapeutic target for metformin." (PMID 39922487, 2025). "Lastly, the bioinformatics analysis suggested that CARM1 may serve as a promising biomarker for assessing sensitivity to chemotherapeutic agents and for predicting outcomes in cancer patients." (PMID 40969596, 2025). "Collectively, these genetic models have provided critical insights into the diverse physiological and pathological functions of CARM1, from tissue-specific differentiation to tumor progression, and have underscored its therapeutic relevance in both developmental disorders and cancers." (PMID 41152553, 2025). "The research highlights the potential of CARM1 as a target for treating diseases such as cancer." (PMID 41152553, 2025). "Multiple functions exerted by PRMT3 and CARM1 in various cancers." (PMID 39964832, 2025). "Therefore, in‐depth studies on the structure and function of CARM1 and the development of effective CARM1 inhibitors are of significant importance for cancer prevention and treatment." (PMID 39964832, 2025). "As CARM1 is overexpressed and functions as an oncogene in various types of tumors, targeting CARM1 may help in cancer treatment." (PMID 40016178, 2025). "A study reported that CARM1, an oncogene, is dysregulated in several types of cancer." (PMID 40016178, 2025). "In cancers, NUP54 induces nuclear import of coactivator-associated arginine methyltransferase 1 (CARM1) and, consequently, transcriptional activation and neurogenic locus notch homolog protein 2 (Notch2) methylation, thereby accelerating GC cell proliferation and tumorigenesis." (PMID 39080077, 2024). "Overall, the diverse expression levels and subcellular localization patterns of various CARM1 isoforms may potentially account for observed discrepancies in the functional roles of CARM1 in cancers." (PMID 38619752, 2024). "Among nine members of PRMT family, PRMT5, PRMT1, and CARM1 are most highly expressed in cancer." (PMID 39711357, 2024).
cancer (continued). "Furthermore, we delve into the regulatory mechanisms exerted by oncogenic signals on the expression, PTMs and enzymatic activity of CARM1 across different cancer types." (PMID 38619752, 2024). "Therefore, SMARCC1 is pivotal as its modification by CARM1 directly impacts gene regulation and cancer progression." (PMID 39468330, 2024). "Oncogenic CARM1 exhibits varying expression levels across different cancer types." (PMID 38619752, 2024). "Moreover, the enzymatic activity of CARM1 undergoes significant changes depending on its isoforms and PTMs within the diverse cancer landscape." (PMID 38619752, 2024). "CARM1 is overexpressed in a variety of cancers, including breast, lung, colorectal, liver, and prostate cancer and because it drives key oncogenic processes, it could be a therapeutic target in these diseases as well." (PMID 38649367, 2024). "CARM1 functions as an oncogene or a tumor suppressor depending on cancer types." (PMID 39567506, 2024). "This remarkable finding suggests that CARM1 could act as a ROS sensor, influencing cancer’s redox balance and metabolism." (PMID 38619752, 2024). "CARM1-mediated H3R17 methylation promotes gene transcription and cell proliferation, which has been linked to the pathogenesis of tumors and unfavorable prognostic outcomes in several cancers, such as breast, lung, and liver cancers." (PMID 38619752, 2024). "CARM1, an important target in cancer, is closely related to tumor cell proliferation." (PMID 37477799, 2023). "Like NFIB, CARM1 is often overexpressed in human cancers, including lung cancer." (PMID 36690626, 2023). "Elevated expression levels of CARM1 have been observed in multiple cancer types such as breast, colon, and prostate suggesting a potential oncogenic role for CARM1 in the context of human cancers." (PMID 37377614, 2023). "Furthermore, in cancer cells, CARM1/PRMT4 inhibition upregulates type I interferon (IFN) and supports the infiltration of natural killer cells and CD8+ T cells into the tumor." (PMID 36980950, 2023). "To explore the role of CARM1 in MM, we analyzed The Cancer Genome Atlas MM dataset to determine whether CARM1 expression correlates with prognosis." (PMID 37477799, 2023). "Thus, CARM1 contributes to cancer by both enzymatic activity–dependent and enzymatic activity–independent functions." (PMID 37377614, 2023). "CARM1 is over-expressed in multiple cancer cell lines and patient samples." (PMID 37477799, 2023). "In the context of short-term, pharmacological CARM1 inhibition as cancer therapy, a temporary lapse in muscle function and performance may be a negligible side effect for an efficacious treatment." (PMID 37493245, 2023). "However, correlative studies have found that CARM1 is elevated in early cancer progression, and further upregulated after androgen ablation therapy, suggesting that targeting CARM1 will have therapeutic value in both contexts." (PMID 37536629, 2023). "Due to the close relationship between CARM1 and cancer, future clinical applications of our research may require targeting peptides for bone formation." (PMID 37649137, 2023). "In animal experiments, considering the correlation between CARM1 and cancer, we did not choose to use adenovirus or adeno‐associated virus but instead used lentivirus injection in the femoral medullary cavity." (PMID 37649137, 2023). "However, researches on CARM1 in cancers are only started in recent years, and limited to several kinds of tumors." (PMID 35033016, 2022). "The CARM1 expression levels in various cancer cell lines were also analyzed." (PMID 35033016, 2022). "Our study conducts a comprehensive analysis of CARM1 in pan-cancer, which could provide clues for detecting its prognostic value and potential immunological function in tumor therapy." (PMID 35033016, 2022). "An integrated analysis of CARM1 in pan-cancer may contribute to further explore its prognostic value and potential immunological function in tumor therapy." (PMID 35033016, 2022).